GPR35 (G protein-coupled receptor 35)
Diseases named in the same sentence as GPR35 in open-access papers (continued):
Sharing a sentence is not in itself a finding about the gene and the disease.
tumor (continued). "In vitro studies using GPR35-deficient (Gpr35-/-) mice in Apcmin and azoxymethane/dextran sodium sulfate (AOM/DSS) models have demonstrated significant reductions in tumor burden, likely due to disrupted NKA-Src signaling and downstream effectors such as ERK1/2 and Akt." (PMID 41459506, 2025). "Additionally, we found that the chemokine CXCL17 and the G protein-coupled receptor 35 (GPR35) were associated with stem cell-like features, detecting undifferentiated CC tumor cells." (PMID 38715790, 2024). "Yet, KA is documented to exert immunosuppressive effects via the G-protein-coupled receptor 35 (GPR35), which may potentiate tumor progression." (PMID 37876966, 2023). "NGB could be a promising strategy for cancer therapy by decreasing tumor metastasis through the suppression of GPR35/angiogenesis axis." (PMID 37005662, 2023). "More importantly, CID showed an inhibitory effect on GPR35-mediated tumor cell malignant phenotype." (PMID 37113762, 2023). "Here, we provide additive evidence to charge GPR35, a marker of aggressive tumor cells." (PMID 37113762, 2023). "Gpr35–/– tumours exhibited much lower gelatinolytic activity compared with Gpr35+/+ tumours." (PMID 33758004, 2022). "Furthermore, according to the database of GTEx (genotype-tissue expression) and TCGA, GPR35 was found that its expression level among macrophage M0 in tumor tissues is far more than that in normal stomach tissues and tumor-adjacent tissues." (PMID 36333291, 2022). "Furthermore, since GPR35 was enriched in immune cells of the blood, the GPR35 function in the tumor immune microenvironment was explored." (PMID 36333291, 2022). "Elevated GPR35 expression has been observed in individuals at increased risk of CRC, and its expression level is significantly correlated with the advanced stage of the tumor and poor prognosis of patients, implicating the receptor in tumor initiation and progression." (PMID 41459506, 2025). "This revision description makes explicit that “GPR35 downregulation” leads to the inactivation of the AKT/HIF-1α signaling pathway, which in turn produces two synergistic anti-tumor outcomes: inhibition of proliferation and promotion of apoptosis." (PMID 41459506, 2025). "GPR35, which scored high in the iTARQ assay, was negatively correlated with NGB and related to tumor angiogenesis." (PMID 37005662, 2023). "Altogether, this demonstrated that GPR35 in LysM+ myeloid cells potently promotes tumour growth in both CRC and CAC, and hinted toward an important role of tumour angiogenesis in this microenvironmental pathway." (PMID 33758004, 2022). "Moreover, CXCL17 and GPR35 might specifically identify less differentiated tumor cells." (PMID 35008827, 2021). "Pharmacological inhibition of GPR35 using TMER1i enhances antitumor immune responses by disrupting Hippo-YAP signaling in T regulatory and cytotoxic T cells, counteracting IDO1-driven immunosuppression in the tumor microenvironment." (PMID 41459506, 2025). "Blocking GPR35 signaling also reduces the secretion of angiogenic factors, including vascular endothelial growth factor (VEGF) and CXCL1, thereby inhibiting tumor angiogenesis and tumor cell proliferation." (PMID 41459506, 2025). "The results seem that GPR35 could be involved in the NGB-OE phenotype, NGB-suppressed tumor angiogenesis and cell metastasis by promoting GPR35 degradation." (PMID 37005662, 2023). "Tumor angiogenesis was activated in response to GPR35 restoration in the NGB absent group." (PMID 37005662, 2023). "Five hypermethylated loci harbored by four genes (GSTP1, TACSTD2, BMP4 and RASSF1) and three hypomethylated loci in three genes (ARHGAP8, GPR35 and DLGAP1) were validated using 7 assays with 12 tumor-normal tissue pairs from this study." (PMID 23437062, 2013).
cancer (19 papers, 2012 to 2026). A tumor composed of atypical neoplastic, often pleomorphic cells that invade other tissues. "GPR35 is an orphan G-protein coupled receptor that has been implicated in the development of cancer." (PMID 40121360, 2025). "To assess GPR35’s impact on ion homoeostasis, we used siRNA to knock down the receptor in a range of GPR35-expressing cancer cell lines." (PMID 40121360, 2025). "Given its role in regulating host responses to microbial signals, GPR35 represents a key node in the inflammation-microbiome-cancer axis." (PMID 41459506, 2025). "Due to its favorable druggable structure and the feasibility of designing high-affinity agonists and inhibitors, pharmacological modulation of GPR35 represents a promising strategy for treating digestive and other cancers." (PMID 41459506, 2025). "This review synthesizes current findings on the role of GPR35 in cancer biology and metabolism and highlights its potential as a therapeutic target for metabolic reprogramming in digestive cancers." (PMID 41459506, 2025). "Mechanistic evidence indicates that GPR35 drives cancer progression by reprogramming cellular metabolism." (PMID 41459506, 2025). "In GC, GPR35 knockdown not only inhibits cancer cell proliferation and migration and promotes apoptosis, but also blocks macrophage polarization to M2 phenotype, suggesting its role as an immune regulation node and potential therapeutic target." (PMID 41459506, 2025). "As research continues to unravel the dual role of GPR35 in metabolic control and oncogenesis, the interplay between GPR35-mediated metabolic adaptations and cancer progression is gaining increasing attention." (PMID 41459506, 2025). "GPR35 mRNA and protein expression is indeed upregulated in a number of cancers, including colorectal, liver and breast." (PMID 40121360, 2025). "Cell proliferation following GPR35 knockdown was significantly reduced across a range of cancer cell lines representing intestinal (Caco-2 and SW480), liver (HepG2), pancreatic (Capan-2) and breast (MCF-7) epithelial cells." (PMID 40121360, 2025). "As previously discussed, GPR35 is highly expressed in various cancers and governs key metabolic processes, particularly glucose and lipid metabolism, during tumorigenesis." (PMID 41459506, 2025). "Specifically, we still do not understand which mechanisms—such as specific ligands, receptor isoforms, or cellular contexts—determine the signaling bias of GPR35 in different cancer types or stages." (PMID 41459506, 2025). "In the present study, we demonstrated that GPR35 overexpression can promotes anchorage-independent cell growth and YAP/TAZ activity, and this pro-cancer role of constitutive GPR35 activity can be effectively inhibited by its antagonist." (PMID 37113762, 2023). "To investigate the pro-cancer function of GPR35, we stably overexpressed GPR35 in DLD1, THC8307, and HCT116 cell lines." (PMID 37113762, 2023). "Here we investigated the cancer-promoting role of overexpressed GPR35 by performing two-dimensional (2D) culture conditions and tree-dimensional (3D) soft-agar anchorage-independent growth of CRC cells." (PMID 37113762, 2023). "GPR35 antagonists are promising anti-cancer agents that target hyperactivation and overexpression of YAP/TAZ in CRC." (PMID 37113762, 2023). "Since RNA modification writers, readers and erasers can have either promoting or inhibitory effects on the hallmarks of cancer, the GPR35 expression level was then further explored the relationship with these signature genes’ expression in GC tissues." (PMID 36333291, 2022). "Based on the TCGA database, these bioinformatics analysis results suggested that GPR35 has promoting effects on the hallmarks of cancer, such as escape apoptosis, achieve replicative immortality, acquire metastatic potential, and evade the immune response." (PMID 36333291, 2022). "Several studies report alterations in the concentration of KYNA and the expression of GPR35 in different cancers." (PMID 33113952, 2020).
cancer (continued). "Despite the fact, that GPR35 agonists have not been directly related to pro- or antiproliferative activity towards cancer cells to date, GPR35 signalling via ERK kinase is involved in several processes including proliferation, cell survival and metastasis." (PMID 31659416, 2020). "In summary, GPR35 has complex and context-dependent mechanisms in cancer." (PMID 41459506, 2025). "Together, these findings support a therapeutic model in which targeting GPR35 and associated glycolytic signaling, particularly through NKA modulation, may offer novel treatment avenues for metabolic reprogramming in cancer." (PMID 41459506, 2025). "While recent reviews have comprehensively summarized the molecular basis of GPR35 in cancer and immunity, as well as advances in its therapeutic targeting, a focused examination of its role in the metabolic reprogramming of digestive system tumors remains unexplored." (PMID 41459506, 2025). "We questioned whether the pro-cancer phenotype exhibited by GPR35 overexpression depends on YAP activity." (PMID 37113762, 2023). "Therefore, future works can be done screening more active GPR35 antagonists for anti-cancer drug development." (PMID 37113762, 2023). "Taken together, we found that GPR35 is an oncogene in GC, which could promote cancer cell proliferation and migration." (PMID 36333291, 2022). "Taken together, high expression level for GPR35 in GC tissues could result in cancer cell proliferation and migration, and leads to some immune cells’ significance exhaustion, macrophage infiltration, and polarization of M2 macrophages." (PMID 36333291, 2022). "Furthermore, for GC, the GPR35 expression level has a significant positive relative to the stemness of cancer cells which is a key feature for cancer progression and, in many cases, the source of cancer cell survival." (PMID 36333291, 2022). "Moreover, the HR values for GPR35 in groups for TNM stages, Lauren classification, and diverse differentiation indicated that GPR35 plays a critical factor in the cancer development of GC." (PMID 36333291, 2022). "On the other hand, KYNA interaction with GPR35 and mentioned signalling pathways may also affect immunological response to cancer cells." (PMID 31659416, 2020). "However, whether targeting GPR35 by antagonists can inhibit its pro-cancer role has yet to be answered." (PMID 37113762, 2023). "While KYNA has been found to be an endogenous activator of GPR35 in humans and rats altering immune responses in inflammation, pain, cancer, cardiovascular disease and energy homeostasis [Reviewed In:], its role as an activator of GPR35 in other species remains unknown." (PMID 35682980, 2022). "Thus, the interaction between KYNA and GPR35 in cancer cannot be excluded." (PMID 31659416, 2020). "In CRC cells, GPR35 inhibits YAP/TAZ phosphorylation, thereby enhancing YAP/TAZ transcriptional activity and promoting anchorage-independent growth of cancer cells, while small molecule inhibitors CID-2745687 and ML145 can effectively block this pathway." (PMID 41459506, 2025). "Along with the classical CB1 and CB2 receptors, other families of GPCRs including GPR119, GPR35, and GPR55 are emerging as novel targets in the treatment of many diseases like cancers and gastrointestinal diseases." (PMID 37834122, 2023). "In summary, we discover a function of agonist-independent constitutive GPR35 activity that promotes YAP/TAZ activity and assists cancer cell growth under detachment." (PMID 37113762, 2023). "Taken together, GPR35 and GPR55 influence the IBD and cancer features such as regulation of inflammation, pain, metabolic changes, and hypoxia." (PMID 37834122, 2023). "The survival plots and HR values suggested that GPR35 is a promote cancer gene, nevertheless, CAPN10 is a suppressor cancer gene in GC." (PMID 36333291, 2022). "The molecular landscape driving cancer progression through GPR35 constitutes a complex and not yet fully connected dynamic network." (PMID 41459506, 2025).
cancer (continued). "Although the significant relevance of GPR35 in cancer progression has been gradually acknowledged, whether GPR35 antagonist is a potential anti-CRC agent has not been investigated yet." (PMID 37113762, 2023). "Furthermore, GPR35 only disclosed its cancer-promoting role in soft agar assay rather than in 2D plate culturing conditions." (PMID 37113762, 2023).
cardiovascular disease (11 papers, 2015 to 2023). "For cardiovascular disease, deletion of GPR35 induced augmentation of EC functions in vitro, enhanced endothelium-mediated vasodilation in isolated vessels, and prevented BP elevation in vivo." (PMID 35087615, 2022). "Nonetheless, several studies have highlighted potential roles for GPR35 in the cardiovascular system and in cardiovascular disease." (PMID 29860395, 2018). "Further evidence of an involvement of GPR35 in cardiovascular disease was found in a global gene expression microarray analysis of twelve individuals diagnosed with chronic heart failure." (PMID 25805994, 2015). "Considering that hypoxia is a feature of most chronic cardiac pathologies, this provides a possible rationale for the apparently broad involvement of GPR35 in cardiovascular disease." (PMID 25805994, 2015). "The emerging relevance of GPR35 in cardiovascular diseases was recently documented." (PMID 37895852, 2023). "Despite the limited evidence of GPR35/CXCR8 cardiovascular system expression, there are reports that suggest GPR35/CXCR8 may play a role in cardiovascular disease." (PMID 25926795, 2015). "Altogether, these reports may suggest that GPR35/CXCR8 may be an important target in the development of novel cardiovascular disease therapies and may act as an early marker of cardiac pathologies." (PMID 25926795, 2015). "For example, kynurenate activates GPR35, a drug target and a GPCR involved in inflammatory responses and cardiovascular disease." (PMID 33757768, 2021). "Although a role for GPR35 in cardiovascular disease is not immediately obvious from its expression profile, the receptor has been implicated, both directly and indirectly, in several aspects of cardiovascular dysfunction." (PMID 25805994, 2015).
infection (8 papers, 2018 to 2025). The state of being infected such as from the introduction of a foreign agent such as serum, vaccine, antigenic substance or organism. "5-HIAA is released by platelets and mast cells at the site of infection, binds to G protein-coupled receptor 35 (GPR35) and causes its expression to be upregulated." (PMID 40278627, 2025). "To test this, we subjected global Gpr35-deficient mice (Gpr35−/−) and Gpr35wt mice to infection with C. rodentium." (PMID 35264769, 2022). "Moreover, whether a deficiency of GPR35 can inhibit inflammatory- or infection-induced IDD needs to be further explored." (PMID 35087615, 2022). "GPR35 signaling results in increased transmigration of GPR35+ neutrophils through the platelet-coated endothelial layer, which are further attracted to sites of infection in response to 5-HIAA released by tissue mast cells." (PMID 37394584, 2023). "CXCL17-deficient mice have also been reported to be less resistant to infection in a mouse model of herpes simplex virus infection, although this was postulated to be a result of impaired trafficking of GPR35+ cytotoxic T cells." (PMID 37942327, 2023). "5-HIAA is released by platelets and mast cells at sites of infection and binds to GPR35, which is upregulated after infection." (PMID 37394584, 2023). "Although the C. rodentium kinetic clearance was comparable between Gpr35−/− and Gpr35wt animals, the bacterial counts were significantly higher in the feces of Gpr35−/− mice between days 3 and 9 post-infection (p.i.)." (PMID 35264769, 2022). "Histologically, the GPR35+/+ mice that survived 3 days of ETBF infection showed mucosal damage, including bleeding, epithelial cell shedding, and ulcerations." (PMID 33990686, 2021). "GPR35 signaling promotes neutrophils to pass through the platelet-coated endothelial cell layer, and these neutrophils are further attracted to the site of infection in response to 5-HIAA released by the tissue mast cells." (PMID 40278627, 2025). "To exclude the possibility that macrophages expressing GPR35 contribute to the clearance of C. rodentium, we investigated whether Gpr35 deletion in macrophages versus ECs affects mice differently during infection with C. rodentium." (PMID 35264769, 2022). "Multiple factors could explain why only a reduction in inflammation was observed in GPR35−/− mice compared to wild-type mice at the initial stage of ETBF infection." (PMID 33990686, 2021). "Thus, infection with ETBF could drive microenvironmental changes that regulate microbe:CEC interactions via separate GPR35-independent pathways." (PMID 33990686, 2021). "Meanwhile, 5-HIAA was found as a ligand or agonist for GPR35, which indicated that the increased 5-HIAA in SFTS patients probably promoted the inflammation during the infection of SFTSV." (PMID 38191404, 2024). "On the other hand, kynurenic acid is an endogenous agonist of gpr35 (which was the second most upregulated gene in β-glucan-stimulated zebrafish in the absence of infection), and its activation increases FAO and induces an anti-inflammatory state." (PMID 30038625, 2018).
metabolic disorders (8 papers, 2021 to 2025). "The disturbed formation of kynurenic acid, which targets glutamate-mediated neurotransmission, GPR35, and aryl hydrocarbon receptors of immune or redox status, was implicated in the development of neuropsychiatric and metabolic disorders among others." (PMID 38255742, 2024). "For example, the inflammation and metabolic disorders caused by blocking calcium mobilization-mediated NLRP3 inflammasome activation via G protein-coupled receptor 35 (GPR35) are ameliorated by kynurenic acid, which is produced by a PLP enzyme, kynurenine aminotransferase, from kynurenine." (PMID 38202006, 2024). "Collectively, these findings establish GPR35 as a key regulator of lipid metabolism and position it as a promising therapeutic target for metabolic disorders characterized by lipid dysregulation." (PMID 41459506, 2025). "Inflammation and metabolic disorders resulting from NLRP3 inflammasome activation via G protein-coupled receptor 35 (GPR35) can be mitigated by kynurenic acid, synthesized from kynurenine by the PLP enzyme kynurenine aminotransferase (KAT)." (PMID 39337450, 2024). "We demonstrate that KA specifically prevents NLRP3 inflammasome activation by mitigating calcium mobilization and mitochondrial damage and mitochondrial ROS production via GPR35, which improves inflammatory diseases and metabolic disorders." (PMID 36311752, 2022). "Thus, KA ameliorated inflammation and metabolic disorders by blocking calcium mobilization-mediated NLRP3 inflammasome activation via GPR35." (PMID 36311752, 2022).
adenocarcinoma (2 papers, 2022 to 2024). A common cancer characterized by the presence of malignant glandular cells. "Prior to examining animal tissue, we explored the constitutive versus agonist-mediated activity of GPR35 in both human HT-29 adenocarcinoma and hepatocyte-like HEPG2 cells." (PMID 39615676, 2024).
bacterial infection (2 papers, 2022). "Our data show that epithelial Gpr35 is essential for host defense against invasive bacterial infection." (PMID 35264769, 2022).
digestive system cancer (1 paper, 2025). A primary or metastatic malignant neoplasm involving any part of the digestive system. "Therapeutically targeting GPR35 to modulate gut microbial interactions could offer a novel approach to preventing or treating digestive system cancers." (PMID 41459506, 2025).
intestinal diseases (1 paper, 2021). "There have been studies on GPR35 in the context of intestinal diseases since its identification as a risk gene for IBD." (PMID 34790192, 2021). "However, before GPR35 can be considered as a pharmaceutical target for the treatment of intestinal diseases, more studies are needed to elucidate the mechanisms governed by GPR35 signaling." (PMID 34790192, 2021).